CRP (C-reactive protein)
Diseases named in the same sentence as CRP in open-access papers (continued):
Sharing a sentence is not in itself a finding about the gene and the disease.
diabetes (continued). "In individuals with type 2 diabetes, CRP (C-reactive protein) levels tend to be higher due to inflammation in certain tissues associated with insulin resistance and other complications of diabetes, such as the risk of cardiovascular disease, a serious complication among people with diabetes." (PMID 39091901, 2024). "In multivariate linear regression analyses, increasing age, female sex, having COPD, and rheumatic disease were associated with higher adiponectin levels, whereas increasing BMI, having diabetes mellitus, and higher admission CRP were associated with lower adiponectin levels." (PMID 38633314, 2024). "The pathophysiology of diabetes and cardiovascular disease has been linked to chronic low-grade inflammation, which is characterized by elevated levels of inflammatory markers like C-reactive protein (CRP) and interleukin-6 (IL-6)." (PMID 38846218, 2024). "Moreover, CRP has been associated with diabetic retinopathy, suggesting its potential role in monitoring diabetes-related complications." (PMID 39091901, 2024). "A nested case-control analysis within a prospective study of 3,842 Swiss adults without baseline diabetes followed for 5.5 years on average showed that diabetes risk increased with highest vs. lowest quartile of baseline IL-6 (OR 1.58 [1.02 – 2.45]) and CRP (OR 4.63 [2.85 – 7.53])." (PMID 38665261, 2024). "The PROSPER study including 4402 elderly people showed that hs-cTnT was positively correlated with age and male sex, as well as with cardiometabolic risk factors, such as BMI, blood pressure, NT-proBNP, CRP, presence of diabetes mellitus, and is inversely correlated with eGFR." (PMID 39685587, 2024). "Elevated CRP levels were significantly associated with diabetes, hypertension, and dyslipidemia." (PMID 38983990, 2024). "Finally, a recent study concluded that the 11β-HSD-mediated glucocorticoid activation in T2D is determined by inflammation (higher CRP) and is associated with diabetes and poorer glycaemic control in patients with CKD stages III–V." (PMID 38638132, 2024). "Several clinical biomarkers incorporated into some of the newer epigenetic clocks are associated with shorter gestational length and an increased risk of preterm birth, including maternal glucose levels/diabetes, creatinine levels/kidney function, and C-reactive protein (CRP)." (PMID 39587618, 2024). "Based on the analysis of 16 randomized clinical trials (RCTs), researchers from China concluded that “anti-inflammatory therapies targeting pathogenic process of diabetes can significantly reduce the level of fasting glucose, HbA1c, and CRP in patients with diabetes”." (PMID 39199336, 2024). "Epidemiological studies have reported that increased DASH-derived dietary scores are associated with reduced CRP in the Cork and Kerry Diabetes and Heart Disease Study, a longitudinal study of a representative sample of the general population of Southern Ireland aged 50–69 years." (PMID 38999806, 2024). "Testosterone, TMPRSS2, and aromatase were independently associated (p < 0.01) with severity after adjusting for several baseline risk variables (including age, sex, CRP, obesity, hypertension, hyperlipidemia, and diabetes) in a multivariate logistic regression model." (PMID 39449074, 2024). "Curcumin could reduce the average concentration of high‐sensitivity CRP in DM patients, suggesting it reduced the risk of diabetes complications by reducing inflammatory reaction." (PMID 38617433, 2024). "In addition, several host factors for mucormycosis (i.e., renal transplantation, diabetes mellitus, and diabetic ketoacidosis), elevated C-reactive protein, and rural residence were also associated with CAM." (PMID 36573628, 2023). "Cross-sectional multivariable regression model between sRAGE levels and clinical traits (history of diabetes and cardiovascular diseases) and inflammatory biomarker levels (Il-6 and CRP) revealed a significant inverse association between circulating sRAGE levels and CRP levels." (PMID 37198231, 2023).
diabetes (continued). "The associations between prediabetes, unknown diabetes, acute-on-chronic hyperglycaemia, and CRP levels, and between admission CRP levels and insulin resistance (IR) in CAP, remain unexplored." (PMID 38202252, 2023). "YKL-40 was positively linked with hyperlipidemia (P = 0.014), diabetes mellitus (P = 0.001), fasting blood glucose (P = 0.045), C-reactive protein (P < 0.001), the Gensini score (P < 0.001), and stenosis degree (graded by the Gensini score) (P < 0.001) in CHD patients." (PMID 38028459, 2023). "However, patients with OSA have a number of confounding factors, such as obesity or diabetes, so increased CRP levels associated with OSA should be taken with precaution." (PMID 37371494, 2023). "Thus, elevated C-reactive protein levels have been associated with an increased risk of the development of diabetes, and LDH is a biomarker of glycemic variability in diabetes monitoring." (PMID 37627906, 2023). "Furthermore, serum CRP is associated with rheumatoid arthritis, obesity, diabetes, cardiovascular disease, and other diseases and can better reflect the inflammatory activity." (PMID 37158532, 2023). "The presence of NOAF has been found to be associated with various factors, including age, diabetes mellitus, hypertension, the left atrial (LA) diameter, N-terminal pro-brain natriuretic peptide, C-reactive protein (CRP), sST2, a Killip class of ≥2, and a final TIMI flow grade of <3." (PMID 37808879, 2023). "Hypertension and diabetes were more common in male subjects compared to female subjects (p < 0.05).Increased physical activity both at baseline and follow up were associated with decreased BMI, WC and inflammatory markers, including us-CRP and TNF." (PMID 37107201, 2023). "Indeed, among patients with non-diabetes, high CRP is associated with the development of type 2 diabetes." (PMID 37081535, 2023). "A major factor that can affect CRP levels seems to be diet, and most studies analyzing CRP values in parallel with underlying medical conditions (mainly cardiovascular issues, metabolic syndrome and diabetes) consider body mass index (BMI) as a factor that possibly increases CRP values." (PMID 37873776, 2023). "Based on a high level of C-reactive protein (CRP), they believe that the pathogeny of diabetes may be insulin resistance caused by inflammation." (PMID 37497212, 2023). "Given that the overweight and obesity conditions were more likely associated with hs-CRP and/or diabetes development, 25–27 the grouping of the small number of underweight with the normal BMI participants should not introduce impactful confounding effects in the model." (PMID 37775289, 2023). "To investigate whether fructose/STZ-induced diabetes is linked with inflammation, we assessed the levels of CRP in the blood-derived serum." (PMID 37237932, 2023). "FSH may also be associated with diabetes through inflammatory markers, such as c-reactive protein, TNF-α, and IL-1β." (PMID 36767197, 2023). "Lower eGFRcrea associated with diabetes, hypertension and higher cholesterol, and with higher CRP and NTproBNP levels, and lower eGFRcysC associated with increasing BMI, hypertension, higher cholesterol, active smoking and with higher CRP and NTproBNP levels." (PMID 37648389, 2023). "After adjusting for age, sex, and ethnicity, only socioeconomic status (OR = 1.02; 95%CI: 1.01–1.03), CRP (OR = 1.02; 95%CI: 1.01–1.02), and history of diabetes (OR = 1.58; 95%CI:1.40–1.78) were significantly associated with accelerated retinal ageing (P < 0.05)." (PMID 36930331, 2023). "The current findings of the positive CRP–diabetes association may inform public health strategies for prevention and surveillance of diabetes in the Nordic region where lifestyle, culture, demography, healthcare and socioeconomic factors resemble Norway." (PMID 37775289, 2023).
diabetes (continued). "After the adjustment of age, gender, race/ethnicity, BMI, hypertension, hypercholesterolemia, diabetes, and CRP level, 25(OH)D deficiency (AOR = 1.48; 95% CI = 1.10–2.00; p < 0.05) and 25(OH)D insufficiency (AOR = 1.25; 95% CI = 1.03–1.52; p < 0.05) remained as the independent risk factors for CVD." (PMID 37630735, 2023). "Moreover, serum Hcy improves risk stratification in patients with diabetes outmatched C-reactive protein." (PMID 36267812, 2022). "Furthermore, the stratification analyses also revealed that among diabetes patients, Hs-CRP level was negatively associated with subsequent cognitive function." (PMID 35936393, 2022). "In univariate analysis, age (> 60 years, odds ratio (OR) = 2.491, p = 0.014), C-reactive protein (CRP, OR = 1.007, p < 0.001), blood sugar (OR = 1.007, p < 0.001), and diabetes mellitus (DM, OR = 4.017, p < 0.001) were significant risk factors for concurrent DNI and CNF." (PMID 35204533, 2022). "After further adjusting for the variables in model 2 plus BUN, creatinine, TG, HDL-c, LDL-c, Hs-CRP, hemoglobin, cystatin C, and HbA1c, diabetes status was a significant risk factor for subsequent cognitive decline (unstandardized β estimate = −0.50, 95%CI = −0.98 ~ −0.02, model 3)." (PMID 35936393, 2022). "This is shown in a study conducted among 4,101 healthy Japanese individuals without diabetes and found that a significant association was observed between elevated serum CRP levels and pre-diabetes, with the inflammation event preceding the progression to type 2 diabetes." (PMID 35757631, 2022). "Since it is unequivocally associated with the development of prediabetes and diabetes-induced vascular complications, the elevated CRP might be an indirect risk factor for T2DM progression." (PMID 35620114, 2022). "A large body of evidence suggests that CRP is closely associated with dyslipidemia, diabetes, cardiovascular disease, and metabolic syndrome, and can be used as an indicator for early screening or long-term monitoring to provide some basis for patient prognosis." (PMID 36418968, 2022). "However, an increased risk of ISR was associated with hs-CRP levels at 6 to 12 months of follow-up, which is higher in studies with diabetes mellitus patients and the elderly." (PMID 36005411, 2022). "In addition, some of the SNPs used were associated with BMI, CRP, coronary artery disease, triglyceride levels, cholesterol levels, blood pressure, diabetes 2 and glycosylated hemoglobin." (PMID 36171422, 2022). "The impact of CRP on mortality may be linked to the burden of co-morbidities (coronary artery disease, diabetes, atrial fibrillation, etc.)with chronic inflammation." (PMID 35244369, 2022). "None of the variables such as age, BMI, drinking, marital status, diabetes, education level, total cholesterol, uric acid, high sensitivity CRP or uric acid significantly modified the associations between quality and rapid eGFRcr − cys decline (P > 0.05 for all)." (PMID 36743175, 2022). "Finally, cardiometabolic risk factors that were associated with incident diabetes were age, BMI, CRP, and triglycerides." (PMID 35509100, 2022). "In addition, CRP plays an important role as a risk factor for age-related diseases such as cardiovascular disease, diabetes mellitus, hypertension, neurological conditions (e.g., Parkinson’s disease, Alzheimer’s disease), and chronic kidney disease." (PMID 35570546, 2022). "We also found that older age, diabetes, heart failure, C-reactive protein level and body mass index impact the risk of adverse outcomes, all of which could be considered in preoperative PEG risk assessment in routine healthcare." (PMID 35902805, 2022). "Moreover, CRP associates positively with an increased risk of insulin resistance and diabetes in adolescents and adults." (PMID 35955698, 2022).
diabetes (continued). "Elevated CRP, BMI, and diabetes are positively associated with hypertension in the elderly, and early screening for CRP and initiation of treatment may help prevent further inflammatory responses in hypertension." (PMID 36418968, 2022). "In this present study, we found that age, SBP, DBP, BMI, TyG index, LDL-C, hs-CRP, smoking, hypertension, diabetes were the risk factors for ischemic stroke, while HDL-C, physical exercise, and taking lipid-lowering drugs were the protect factor for ischemic stroke." (PMID 35505313, 2022). "Previous studies have shown that the most serious risk factors for PAD were diabetes and smoking; others included advanced age, hypertension, and hyperlipidemia; potential risk factors included CRP, fibrinogen, homocysteine, apolipoprotein B, lipoprotein (a), and elevated plasma viscosity." (PMID 36514151, 2022). "In the multivariable model, none of the covariates including age above 60 years, female sex, CRP>50 mg/L, O2 saturation<90%, underlying cardiovascular disease, hypertension and diabetes mellitus, and beta-blockers were associated with Remdesivir-induced bradycardia." (PMID 36733376, 2022). "After a 6-year follow-up, women with the highest CRP values (stratified into tertiles), had an increased relative risk of developing metabolic syndrome and diabetes, and the risk changed minimally after adjusting for Body Mass Index (BMI) and insulin resistance." (PMID 36304737, 2022). "Diabetes is associated with higher CRP levels, similar to our findings." (PMID 35967091, 2022). "Additionally, we found that age, diabetes, heart failure, C-reactive protein and body mass index all impact the risk of adverse outcomes." (PMID 35902805, 2022). "Besides, low-grade systemic inflammation was associated with diabetes, and previous studies indicated that CRP was an independent predictor of cardiovascular risk in the population with diabetes." (PMID 36158788, 2022). "Moreover, it has been reported that C-reactive protein and IL-6 are associated with hyperglycemia and the development of diabetes and that the presence of a high level of Fe favors inflammatory responses." (PMID 33920401, 2021). "Thus, more systemic inflammatory circulating markers such as IL-6, TNF-α, and CRP levels significantly increased and were detrimentally respective to the risk and the development of type 2 diabetes mellitus." (PMID 34917685, 2021). "Subclinical systemic inflammation contributes to the etiology of insulin resistance, which may explain the increased diabetes risk associated with elevated CRP concentrations prospectively." (PMID 33628645, 2021). "A multivariate analysis revealed that underlying diabetes mellitus, hypoalbuminemia, high baseline high-sensitivity C-reactive protein (hs-CRP) and procalcitonin levels, and large maximal abscess diameter were independent factors associated with prolonged hospital stay." (PMID 33573593, 2021). "A prospective investigation including patients with type 2 diabetes mellitus found that baseline omentin positively correlated with changes in arterial stiffness within one year, even after adjusting for classical cardiovascular risk factors and CRP." (PMID 34202323, 2021). "Studies show that a number of factors associated with diabetes, such as high glucose, adipokines, modified lipoproteins and free fatty acids may trigger CRP production by endothelial and smooth muscle cells and monocytes/macrophages." (PMID 34803906, 2021). "In addition to BMI, the effect represented by hs-CRP was also a significant mediator of HF risk in diabetes." (PMID 34583686, 2021). "Other conditions such as periodontal diseases, cardiac inflammation, obesity and renal dysfunction may also be associated with raised CRP levels this is a limitation for the use of these biomarkers for monitoring in diabetes mellitus." (PMID 33676486, 2021).
diabetes (continued). "It showed significant associations of the score with diabetes, smoking habit, hypercholesterolemia, aging, and CRP at the multivariate regression analysis, suggesting the potential use of the Oxidative-INDEX in preventing, diagnosing, and treating coronary artery disease." (PMID 34356365, 2021). "CRP is mainly used as a marker of inflammation and is associated with diabetes." (PMID 34681126, 2021). "Linear regression models were used to analyse the association between SEP and cystatin C as well as the impact of cardiovascular risk factors (i.e., body mass index, blood pressure, blood glucose, diabetes mellitus, blood lipids, C-reactive protein, smoking) on this association." (PMID 34588554, 2021). "The findings represent that the increased mortality associated with increased C-reactive protein levels and prevalence of comorbidities (hypertension, diabetes, etc.)are also in line with other estimates, suggesting that our data are comparable with other populations." (PMID 34289910, 2021). "A variety of inflammatory factors, including C-reactive protein (CRP) and interleukin (IL) -6, not only regulate themselves and other tissues, but also are associated with insulin resistance and islet cell dysfunction, promoting the occurrence of diabetes." (PMID 33722242, 2021). "Studies have shown that there is an association of inflammation with diabetes where there is an increase in the circulating levels of inflammatory markers, including C reactive protein (CRP), interleukin-6 (IL-6), and fibrinogen, which lead to insulin resistance." (PMID 33440707, 2021). "Higher triglyceride was associated with higher serum C-reactive protein, and further adjustment for serum C-reactive protein did not materially change the association between fasting triglyceride and diabetes mortality." (PMID 34930280, 2021). "Data from a meta-analysis reveals that T2DM (type 2 diabetes mellitus) risk as a whole was solidly correlated with increased levels of inflammatory cytokines such as interleukin (IL) 1β, IL-6, IL-18, C reactive protein (CRP) and tumor necrosis factor-α (TNF-α)." (PMID 34829612, 2021). "Second, daytime napping was positively associated with inflammatory markers, including serum C reactive protein, which might enhance the development of diabetes." (PMID 33557863, 2021). "Multivariate cox regression analysis revealed that older age, male, old tuberculosis, diabetes mellitus, higher C-reactive protein, and cavity were positively associated with mortality, while higher body mass index and M. avium infection were negatively associated with mortality." (PMID 33441977, 2021). "The MLRA showed that CRP levels were negatively associated with sex (β = –0.133, p = 0.001), but positively associated with age (β = 0.144, p = 0.000), hypertension (β = 0.099, p = 0.03) and diabetes (β = 0.141, p = 0.01)." (PMID 33770147, 2021). "Furthermore, C-reactive protein (CRP), a general marker of chronic low-grade inflammation, is associated with multiple chronic diseases including diabetes." (PMID 34527591, 2021). "In participants with CRP concentrations ≤10 mg/L (n=4962), higher CRP Z-score concentration was significantly associated with higher odds of diabetes in both the unadjusted (OR 1.31; 95% CI 1.22 to 1.42, p<0.001) and fully adjusted (AOR 1.24; 95% CI 1.14 to 1.36, p<0.001) models." (PMID 32665312, 2020). "Therefore, we studied the relation between the inflammatory infiltrate in the left atrium with clinical risk factors of AF (age, gender, diabetes, and CRP blood levels), comparing paroxysmal and long-standing persistent/permanent AF." (PMID 32072262, 2020). "CRP is mainly used as a marker of inflammation and has been proven to be associated with diabetes." (PMID 32393255, 2020). "Higher CRP levels are also known to be associated with the risk of diabetes." (PMID 32733466, 2020). "Some studies have demonstrated a positive association between hs-CRP level and diabetes." (PMID 33679598, 2020).